VHL (von Hippel-Lindau tumor suppressor)
Diseases named in the same sentence as VHL in open-access papers (continued):
Sharing a sentence is not in itself a finding about the gene and the disease.
renal carcinoma (continued). "We also examined a second VHL defective renal cancer cell line and subline expressing VHL derived from a different patient (RCC4 and RCC4/VHL)." (PMID 21791076, 2011). "PHD3 catalyzes hydroxylation of PKM2 and PHD3 knockdown reduced expression of the HIF-1 target genes SLC2A1, LDHA, and PDK1, and reversed the Warburg effect in VHL-null RCC4 renal carcinoma cells." (PMID 21709315, 2011). "Previously it has been shown that HIF-1α has anti-proliferative effects in VHL defective renal cancer cells." (PMID 21386837, 2011). "HIF-1α downregulation induced by zinc was ineffective in human RCC4 VHL-null renal carcinoma cell line; likewise, the HIF-1αP402/P564A mutant was resistant to zinc treatment." (PMID 21179202, 2010). "Given the central role of VHL in renal cancer formation, we examined the VHL-dependent regulation of miRNAs in renal cancer." (PMID 20964835, 2010). "The level of one HIF- and VHL-regulated miRNA, miR-210, showed marked increases in expression in the renal cancer tissue, and expression levels were correlated inversely with patient survival." (PMID 20964835, 2010). "miRNA dysregulation has been observed in renal cancer, and miR-210 has been identified as a hypoxia and VHL-regulated miRNA in renal cancer cells." (PMID 20964835, 2010). "Reintroduction of wild type VHL into VHL−/− renal carcinoma cells (RCC) suppresses tumor formation in vivo." (PMID 20300531, 2010). "VHL is a well-known tumour suppressor gene and VHL disease is characterised by a distinct subset of highly vascular tumours, notably renal carcinoma, angiomas, and hemangioblastomas." (PMID 20461086, 2010). "Given the central role of VHL in hypoxic gene regulation and in renal cancer formation, we wished to examine the VHL-dependent regulation of miRNAs in renal cancer." (PMID 20964835, 2010). "We wished to understand the mechanism underlying such alterations, examine the extent to which VHL-mediated alterations in miRNAs were HIF-dependent or independent and examine for the utility of miRNA alterations in renal cancer diagnosis." (PMID 20964835, 2010). "Renal cancer occurs in 25–45%of patients with VHL; if cystic lesions are included in this estimate, theincidence increases to over 60%." (PMID 18695737, 2008). "HLRCC-associated renal tumorsappear to represent a significantly more aggressive type of renal cancer thanthat in patients with VHL, HPRC, or BHD." (PMID 18695737, 2008). "Restoration of VHL function is sufficient to suppress in vivo tumor formation in VHL-defective renal carcinoma cells." (PMID 17598890, 2007). "Downregulation of HIF-2α levels by shRNA has been shown to be sufficient to suppress tumor growth of VHL-defective renal carcinoma cells in nude mice." (PMID 17598890, 2007). "The global gene array has shown that essentially all hypoxia-regulated genes are regulated by VHL in renal cancer contributing to an understanding of tissue selectivity of transformation." (PMID 15026807, 2004). "Notably, increased FBXW7 mutations were observed in patients of African descent, while VHL and PBRM1 mutations were decreased in African-origin renal cancer patients." (PMID 40564200, 2025). "Currently there is no experimental evidence that these predicted m6Ad-SNVs influence m6A modification of the transcript; however, limited biochemical evidence suggests ClinVarID 2224 in VHL might increase protein amount in 786-O renal carcinoma cells." (PMID 38769304, 2024). "We found that VHL knockdown could lead to reduced cilia frequency in VHL-wt ccRCC cells, implicating an indispensable role for VHL in maintaining ciliogenesis in renal cancer cells." (PMID 39389955, 2024).
renal carcinoma (continued). "Although our patient tested negative for 19 genes known to cause renal cancer syndromes, including FH, VHL, FLCN, and MET, the possibility that the patient has a coexisting autosomal dominant renal cancer syndrome is unlikely but cannot be excluded." (PMID 38802873, 2024). "The VHL–HIF–VEGFR–mTOR signaling pathway plays a crucial role in the pathogenesis of renal cancer." (PMID 39092291, 2024). "Moreover, the PI3K/AKT/mTOR pathway is frequently hyperactivated in renal cancer, often in conjunction with VHL–HIF signaling, creating a distinctive therapeutic vulnerability." (PMID 39092291, 2024). "The VHL gene is one of the most important tumor suppressor genes in renal cancer." (PMID 39092291, 2024). "The PI3K/Akt signaling pathway was reported to be activated in various renal cancer cell lines regardless of the VHL deficiency." (PMID 38680858, 2024). "Moreover, this pathway synergistically promotes renal cancer progression in cooperation with other signaling pathways, such as the VHL–HIF pathway, while also being intricately regulated by ncRNAs, including miRNAs." (PMID 39092291, 2024). "To test whether VHL regulated primary cilium formation, we established a VHL-knock-down renal cancer cell line (SN12-PM6) using stable RNA interference and analyzed the cilia frequency." (PMID 39389955, 2024). "Additionally, we investigated the impact of VHL, a key gene in renal cancer, and LC3C, an autophagy-related gene, on LAMP1 expression through molecular biology experiments to elucidate the potential underlying mechanism." (PMID 39669571, 2024). "In cells lacking or mutated in VHL, as is often the case in renal carcinoma, HIF activation is observed even in the absence of hypoxia." (PMID 36672719, 2023). "Our finding provided further resolution to a longstanding question: why does destruction of HIF-1α in VHL-deficient renal cancer cells not occur during chronic hypoxia." (PMID 37777750, 2023). "Overall, we assume that the loss of VHL and PTEN may cooperatively contribute to the accelerated progress of renal cancer." (PMID 37445575, 2023). "Deletion of the von Hippel-Lindau (VHL) tumor suppressor gene in renal cancer cells leads to the accumulation of HIF-1α and an increase in Clut2 expression, which promotes aerobic glycolysis in renal cancer cells and leads to metabolic reprogramming of renal cancer cells." (PMID 35251009, 2022). "We show how these VHL mutants stabilize HIF2α, and thereby influence HIF2α-target gene transcriptional program as the major mechanism on signaling pathway activation of hypoxia, glycolysis and epithelial-mesenchymal transition in renal carcinoma cells." (PMID 35505422, 2022). "An early study showed that both CA9 and CA12 expression could be suppressed in renal carcinoma cell lines by expression of the wild-type VHL gene." (PMID 35582034, 2021). "Other genes were also increased in GC tissues, for example, ZNF350 (ZBRK1) was upregulated in GC tissues, and it was reported that ZNF350 could activate VHL gene transcription through formation of a complex with VHL and p300 in renal cancer." (PMID 34594359, 2021). "Similarly, VHL-based PROTACs have been successfully used to degrade SMAD3 proteins in renal carcinoma and renal fibroblast cells." (PMID 33418880, 2021). "In addition, we proposed therapeutic potentials of eIF4A inhibitors against renal cancer with intact VHL gene, which definitely worthied further investigations." (PMID 32826868, 2020). "Doxazosin and DZ-50 were both found to exert potent antitumor action against human renal cancer cell lines 786-0 (harboring a VHL tumor-suppressor gene mutation and a highly angiogenic phenotype) and Caki cells (without a VHL mutation)." (PMID 32872127, 2020).
renal carcinoma (continued). "Silencing of the VHL tumor-suppressor gene by DNA methylation in renal carcinoma." (PMID 32399356, 2020). "We further quantified SNHG12 expression in our available renal cancer cell lines regardless of the mutation status of VHL." (PMID 31114448, 2019). "Finally, we discovered a correlation between VHL inactivation and reduced HR gene expression in a large panel of human renal carcinoma samples." (PMID 29435132, 2018). "VHL inactivation is a key oncogenic event for renal carcinomas." (PMID 30006568, 2018). "We first evaluated the expression level of both Src and Akt proteins and their respective activated forms in the renal carcinoma cells 786-O VHL- cells, and its derivate containing a functional VHL construct HA-VHL (786-O VHL+), together with a normal renal cell line (RPTEC)." (PMID 30046388, 2018). "In contrast, STF-62247 is a cell-permeable autophagy inducer that selectively induces non-apoptotic cell death in VHL-deficient, but not VHL-expressing, renal carcinoma cells (RCC) both in vitro and in vivo." (PMID 29963226, 2018). "The VHL status was assessed in 55 primary renal cancers by direct sequencing." (PMID 30514329, 2018). "In addition, miR-1826 down-regulation was found in bladder cell lines and cancers and in von Hippel-Lindau (VHL)-inactivated renal cancer cells." (PMID 26646588, 2016). "Large-scale NotI-microarray analyses of genetic and epigenetic alterations in the genes of chromosome 3 in RCC revealed that leucine-rich repeats containing 3B (LRRC3B) and Von Hippel-Lindau (VHL) genes possess the highest frequency of deletions and/or methylations in renal carcinoma." (PMID 27725787, 2016). "Owing to its target potency and favorable pharmacokinetic properties, MTI-31 inhibited mTOR signaling function in vivo and demonstrated single agent oral antitumor efficacy in tumor models of HER2+/PIK3CAmut breast cancer, PTEN/VHL-null renal cancer and others." (PMID 27563814, 2016). "We further establish the utility of these lines for the study of renal cancer biology (a malignancy of the renal tubular epithelium) by generating models of renal specific deletion of the von Hippel-Lindau (VHL) gene, the most common genetic change found in human renal cancer." (PMID 26866916, 2016). "A previous study showed that 1-butanol, but not tertiary butanol, suppressed HIFα expression in VHL-deficient renal cancer cells." (PMID 25361009, 2014). "Most renal cancers had defects in the VHL tumor suppressor pVHL." (PMID 25091575, 2014). "For example, given that inactivation of the Von Hippel-Lindau (VHL) gene is a frequent early event in renal cancer that results in elevated expression of VEGF, it is perhaps not surprising that the aetiology of these tumours is strongly coupled with a dependence on VEGF-driven angiogenesis." (PMID 24482243, 2014). "Nevertheless, the connection of VHL to a tumor suppressor that regulates a metabolic pathway in renal cancer may reveal a novel aspect of VHL tumor-suppressing activity that is complementary to its roles in the regulation of angiogenesis and autophagy." (PMID 23922894, 2013). "However, significant up-regulation of VHL occurs in renal carcinoma cells and cytotrophoblasts under hypoxic conditions and in renal proximal tubule epithelial cells under ischemia/reperfusion injury." (PMID 23785396, 2013). "In addition, FLCN mRNA and protein expression were repressed in Caki1 renal cancer cells in which we knocked down endogenous VHL expression by using shRNA." (PMID 23922894, 2013). "While loss of the tumor suppressor gene von Hippel Lindau (VHL) is thought to be an initiating event for the majority of RCCs, a role for FH in sporadic renal cancer has not been explored." (PMID 21695080, 2011).
renal carcinoma (continued). "In addition, mTOR signaling complex 2 (mTORC2), a known activator of AKT signaling, has been shown to promote HIF-2α accumulation in VHL null renal carcinoma cells." (PMID 21695080, 2011). "von Hippel-Lindau itself in the absence of RCC did not lead to significant differences in overall CEC numbers, suggesting that the development of renal cancer, and not merely the presence of VHL mutation, is associated with the increase in CEPs." (PMID 21673679, 2011). "In the renal carcinoma tissue harbouring the A3243G mutation as well as in the two other renal carcinoma tissues investigated, lack of VHL protein was observed." (PMID 16404428, 2006). "The tissue selectivity of VHL transformation in renal cancer may be related to the tissue-specific direction of regulation of this key checkpoint by hypoxia." (PMID 15026807, 2004). "Furthermore, immunoprecipitation studies using renal carcinoma cell extracts have indicated that VHL binds to fibronectin." (PMID 15361934, 2004). "Interestingly, VHL-defective renal carcinoma cells demonstrate a variety of matrix-related abnormalities, including abnormal fibronectin assembly, defective formation of fibrillar adhesions, and changes in branching morphogenesis and migration." (PMID 15361934, 2004). "Therefore, to ensure that the methylation changes seen across renal cancers were not due to the confounding effect of VHL and other mutations, we selected a group of pan-negative WT samples by excluding samples with VHL, BAP1, or PBRM1 mutations." (PMID 37528416, 2023). "We were interested in whether VHL levels in renal cancer correlated with PD-L1 levels." (PMID 36267974, 2022). "To confirm the selective involvement of HIF-2α, but not that of HIF-1α, in the H19 downregulation, we evaluated changes in the H19 response to combined treatment in the VHL-deficient renal carcinomas cells (786-O) that express endogenous HIF-2α, but not HIF-1α." (PMID 31426484, 2019). "Thus we can speculate that NKs from VHL-MUT-RCC patients are more efficient toward human renal cancer VHL-MUT cells." (PMID 30514329, 2018). "VHL is not frequently mutated in skin cancer as compared to, e.g., renal cancers." (PMID 28806730, 2017). "Similarly, silencing of EGFR decreases VHL-dependent renal cancer growth." (PMID 26027747, 2015). "Interestingly, FLCN, like tumor suppressor VHL, seems to be associated with the activity of LC3-mediated autophagic program, which suggests that the existence of functional crosstalk between two major tumor suppressors in renal cancer, VHL and FLCN, converging on regulation of autophagy." (PMID 24305604, 2013). "While VHL loss is clearly critical to HIF-2α stabilization, alternate mechanisms, besides the prevention of degradation, may play a role in the maintenance of HIF-2α in renal cancer." (PMID 21695080, 2011). "Interestingly, in renal cancer, low CA IX expression and absence of VHL mutation were related to a more advanced tumour and unfavourable outcome." (PMID 19240720, 2009). "We utilized a renal cancer cell line model, comparing LPCAT1 expression in three VHL-mutant cell lines (A-498, 786-O, and OS-RC-2) against the HK-2 control." (PMID 39781455, 2025). "In summary, the VHL–HIF–VEGFR–mTOR signaling pathway plays a crucial regulatory role in the initiation and progression of renal cancer." (PMID 39092291, 2024). "Metabolic reprogramming in renal cancer is mainly triggered by the activation of the Ras-PI3K-AKT-mTOR pathway and the inactivation of the von Hippel-Lindau (VHL) gene." (PMID 38884097, 2024). "Nine individuals were included because they were diagnosed with a syndromic form of renal cancer (BHD (n = 5), VHL (n = 3), and HLRCC (n = 1))." (PMID 38002934, 2023).
renal carcinoma (continued). "The main aim of this review is to present renal cancer types, dysregulation of PI3K/AKT/mTOR signaling pathway members, crosstalk with VHL/HIF axis, and carbohydrates, lipids, and amino acid alterations." (PMID 37176098, 2023). "Inactivation of the VHL gene and activation of the HIF-VEGF pathway are the major molecular hallmarks of renal carcinoma and form the basis of antiangiogenic therapy such as sunitinib." (PMID 34503211, 2021). "NMU expression was tested in two VHL-defective renal cancer cell lines (i.e., RCC4 and RCC10) and their sublines with stable overexpression of VHL." (PMID 31492042, 2019). "IL-2 activated whole-blood samples (28 VHL-WT-RCC and 23 VHL-MUT-RCC) were evaluated for NK cytotoxicity toward human renal cancer cells A498, VHL-MUT and CAKI-1, VHL-WT." (PMID 30514329, 2018). "In summary, with the current study, we have provided first evidence for a direct connection between the VHL and FLCN tumor-suppressing pathways converging on regulation of autophagy in renal cancer." (PMID 23922894, 2013). "This convergence in the functions of VHL and FLCN is of special interest considering the fact that clear cell carcinoma can be part of the multihistological type of renal cancer that occurs in BHD syndrome." (PMID 23922894, 2013). "Renal cancer cells and sublines expressing VHL (RCC10, RCC4, RCC10/VHL, RCC4/VHL) were loaded with a calcium sensitive fluorescent dye prior to treatment with exogenous NMU peptide." (PMID 21791076, 2011). "In the three renal cancer cell lines tested, RCC4-wt vHL demonstrated an increase in mRNA and protein expression of PDK-1." (PMID 18542064, 2008). "Eachinherited cancer syndrome, such as VHL, HPRC and hereditary leiomyomatosis andrenal cell carcinoma (HLRCC), is characterized by the development of specifichistologic types of renal cancer." (PMID 18695737, 2008). "Notably, there is significant crosstalk between the VHL–HIF–VEGFR–mTOR and PI3K/AKT/mTOR pathways, forming a complex signaling network that synergistically promotes renal cancer progression." (PMID 39092291, 2024). "Most importantly, novel therapies for renal cancer have been developed targeting the VHL-HIF pathway; thus, broad profiling of VHL aberrations may open the possibility to administer these drugs to a wide range of patients." (PMID 37999735, 2024). "The VHL–HIF–VEGFR–mTOR pathway, driven by VHL gene inactivation and subsequent HIF accumulation, promotes tumor angiogenesis, cell proliferation, and metastasis in renal cancer." (PMID 39092291, 2024). "Within ccRCC specifically, Jade-1 expression has been shown to be prognostic for renal cancer regardless of VHL expression." (PMID 37175531, 2023). "In renal cancer cells lacking the VHL gene, the newly expressed VHL produced resistance to iron death." (PMID 36105937, 2022). "Renal cancer cells lacking the VHL gene can form normal-sized tumors in nude mice, and the tumors formed after the introduction of wild-type VHL genes become significantly smaller, and even do not form tumors." (PMID 35035522, 2022). "In renal carcinoma cell lines, ERα serves as a proteasomal degradation target of the VHL protein, however, in the absence of VHL (e.g., ccpRCC) it does not undergo sequestration, but it promotes cell proliferation, enhancing the expression of miR-18a." (PMID 35008576, 2021). "In renal cancer, CHIP targets transglutaminase 2 (TG2), a negative regulator of VHL." (PMID 34831344, 2021). "For example, the constitutive HIF expression in renal cancer cells defective in VHL does not correlate with sensitivity to Ad5 infection." (PMID 32244697, 2020). "Renal cancer cells with VHL defects presented a high expression of NEK8, suggesting that VHL may downregulate NEK8 in these cells." (PMID 32294979, 2020). "Neither repressing nor promoting effects of NMU on cell proliferation were observed in renal cancer cells (RCC10/VHL cell line) nor in pancreatic cancer cell lines (Capan1, SU86.86, MiaPaca2, Panc1)." (PMID 31492042, 2019).